PDGFRB (platelet derived growth factor receptor beta)
Diseases named in the same sentence as PDGFRB in open-access papers (continued):
Sharing a sentence is not in itself a finding about the gene and the disease.
tumor (continued). "LOX enzymatic activity is reported to drive tumour angiogenesis by activating PDGFRβ signalling in vascular SMCs, which is consistent with our DEG analysis that FL SMCs expressed PDGFRB at high levels." (PMID 35332263, 2022). "To validate tumor cell PDGFRB as a prognostic factor, we used an AI‐based deep convolutional neural network method." (PMID 33955203, 2021). "It should also be remembered that PDGFRL, which is also a specific agonistic ligand for PDGFRβ, is known to have potential tumor suppressor activity." (PMID 33524869, 2021). "Given the strong tumour expression of PDGFRB and histologic features reminiscent of pericytic differentiation, pericytes are the proposed cells of origin of myofibroma." (PMID 33830670, 2021). "We observed general aberrant hypervascularization within the tumor mass and increased density of PDGFRβ+ stromal cells across all three patient samples analyzed." (PMID 34535655, 2021). "Our study is the first to show the effect of tumor cell‐specific PDGFRB expression on patient overall survival in two larger patient cohorts." (PMID 33955203, 2021). "Since protumorigenic pathways associated with PDGFD expression were enriched in BLCA, we next determined the relationship between tumor expression of PDGFD or PDGFRB and BLCA patient prognosis." (PMID 34858395, 2021). "In multivariable analysis, unfavorable tumor architecture (HR = 3.20, 95% CI = 1.32–7.76; p = 0.010) and high tumor cell PDGFRB expression (HR = 1.02, 95% CI = 1.00–1.03; p = 0.006) were independently associated with shorter survival." (PMID 33955203, 2021). "We also noted p18−/−;Brca1+/− tumor cells that had invaded into muscles were marked by high levels of Pdgfrβ expression." (PMID 33478572, 2021). "Of note, we see a striking shift from a prevalence of PDGFRα+ fibroblasts in healthy mammary fat pads, to PDGFRβ+ CAFs in tumour tissue." (PMID 34016130, 2021). "Due to the statistically stronger correlation of tumor cell PDGFRB and survival, we validated its prognostic value using an AI model (Aiforia® platform) and showed that a high relative PDGFRB tumor cell positivity correlated with shorter survival." (PMID 33955203, 2021). "The treatment of regorafenib and PDGFRβ antibodies significantly decreased the number of PDGFRβ+ tumour perivascular cells." (PMID 34035882, 2021). "On the other hand, as the tumour develops, the tumour becomes highly enriched in PDGFRβ+ CAFs, while dramatically decreasing the numbers of PDGFRα+ CAFs." (PMID 34016130, 2021). "Overall, the presented data motivates the experimental investigation of paracrine signaling initiated through stromal PDGFRb expression on tumor progression and resistance to RT." (PMID 33661437, 2021). "The result of this rearrangement is the upregulation of COL1A1-PDGFB fusion proteins that are processed to form mature PDGFB and then to activate PDGFRB to form an autocrine loop, rendering tumor cell proliferation and survival dependent on PDGFRB signaling." (PMID 34362454, 2021). "We found that 8.8% of GFPpos (Pdgfrβ KO) tumor cells were positive for annexin V compared to 4.3% of the GFPneg (Pdgfrβ WT) cells." (PMID 33478572, 2021). "Overall, type A pericyte-derived cells accounted for 13 ± 2% of all PDGFRβ+ cells in the tumor mass." (PMID 34535655, 2021). "A study on the effects of lox expression on tumor-driven angiogenesis, demonstrated that the regulation of mRNA and protein expression was carried out through the platelet-derived growth factor β (PDGFRβ)-mediated activation of protein kinase B (Akt)." (PMID 34943209, 2021). "PDGFRβ is highly expressed in many tumors, playing a key role in activating angiogenesis and regulating tumor interstitial fluid pressure." (PMID 33918836, 2021). "The Spearman's rank correlation coefficient between the mfIHC (tumor cell PDGFRB intensity) and AI results (tumor cell PDGFRB area) was 0.489 (p < 0.001)." (PMID 33955203, 2021).
tumor (continued). "In this tumor, EphB4 signaling can be induced by its ligand EphrinB2 or by the cross-talk with PDGFRβ, which facilitates PDGF ligand-dependent, ephrin ligand-independent activation of EphB4." (PMID 34440844, 2021). "In contrast, the small molecule dasatinib, which inhibits both EphB4 and its partner PDGFRβ, resulted in a significant inhibition of in vitro tumor cell viability as well as decreased in vivo tumor growth and significantly prolonged survival." (PMID 34440844, 2021). "Higher LGG tumor expression levels of PDGFRB alone displayed a trend towards poor survival when PDGFD expression was low, but this was not statistically significant." (PMID 34539622, 2021). "The study assessed that a combination of high OX40-L and low PD-1 mRNA levels, high PDGFRB, and low CD3E mRNA levels are associated with increased tumor recurrence." (PMID 34490084, 2021). "In particular for PDGFRβ, which has also been described to be expressed by tumor stroma, further studies are needed to assess the consequence of this for diagnostic or therapeutic purposes." (PMID 34522225, 2021). "Numerous studies into the molecular events driving GBM highlight the central role played by the Epidermal Growth Factor Receptor (EGFR), as well as the Platelet-derived Growth Factor Receptors PDGFRA and PDGFRB in tumor initiation and progression." (PMID 34830952, 2021). "IF revealed CXCL12 in both PDGFRα+ and PDGFRβ+ cells in tumor stroma, as well is in the adjacent matrix and blood vessels." (PMID 33753872, 2021). "We also looked into the prognostic value of tumor cell PDGFRB separately in tumor architecture groups." (PMID 33955203, 2021). "Still, given the strong association between PDGFRB and survival in our study, clinical trials including more patients with more specific PDGFRB inhibitors and AI‐based PDGFRB in situ analysis of patient tumor tissue are warranted." (PMID 33955203, 2021). "The expression of COL1A1, COL4A1, COL12A1, and PDGFRB were all negatively correlated with tumor purity." (PMID 35111208, 2021). "The PDGF family can bind to the tyrosine kinase receptors, PDGFRα and PDGFRβ, and interacts with different cell types within the tumor microenvironment to enhance tumor progression and chemoresistance." (PMID 34195085, 2021). "We were also interested in genes associated with promoting tumor growth and found several that were downregulated in the AS STRAP KO cells, notably platelet-derived growth factor receptor ß (PDGFRβ)." (PMID 34206917, 2021). "In the current study, we found that phosphorylation of PDGFRβ was present in only 33% of UC tumor tissues and 25% of UC cell lines." (PMID 34600548, 2021). "To test the impact of Pdgfrβ CRISPR/Cas9 KO on tumor cell viability, we performed annexin V staining." (PMID 33478572, 2021). "We next transplanted freshly FACS-sorted Pdgfrβ WT and Pdgfrβ KO p18−/−;Brca1MGKO tumor cells that were viable into MFPs of NSG mice." (PMID 33478572, 2021). "The results revealed that COL1A1, COL4A1, COL12A1, and PDGFRB were all negatively correlated with tumor purity." (PMID 35111208, 2021). "Pericyte coverage is regulated by PDGFs family molecules and inhibiting PDGFRβ in combination with antiangiogenic drugs can reduce pericyte coverage and inhibit tumor growth in mouse model P-NETs." (PMID 34885091, 2021). "Genes in the high expression groups, namely, COL1A1, COL4A1, COL12A1, and PDGFRB, were all enriched in the MAPK and PI3K–Akt signaling pathways, which are closely associated with tumor cell proliferation, invasion, and cell cycle." (PMID 35111208, 2021). "Again, these results confirm that the inhibition of Pdgfrβ and Pkcα activity promotes MET and reduces Brca1-deficient tumor initiating potential." (PMID 33478572, 2021). "PDGFRB expression in MPM tumor cells provides a potential target for tyrosine kinase inhibitors (TKIs)." (PMID 33955203, 2021).
tumor (continued). "The ratio between PDGFRB‐positive tumor cell area and total tumor cell area ranged from 0.1 to 98.1%, with a median of 1.9% (IQR: 0.3–13.5%)." (PMID 33955203, 2021). "In sum, these results suggest that inhibition of Pdgfrβ or Pkcα activity suppresses tumor progression by reducing mesenchymal features and inducing apoptosis." (PMID 33478572, 2021). "All markers showed temporal changes with a distinct switch from primarily PDGFRα+ fibroblasts in healthy mammary tissue to predominantly PDGFRβ+ CAFs in tumours." (PMID 34016130, 2021). "Collectively, depletion of PDGFRβ+ or α‐SMA+ perivascular cells impaired tumour revascularization after the discontinuance of AA‐TKI treatment." (PMID 34035882, 2021). "In mice treated with gluconate, there was an overall decrease in the expression of PDGFRβ and vimentin particularly at the tumour–stroma interface." (PMID 33758075, 2021). "Strong Pdgfrβ expression ranged from 2 to 60% of p18−/−;Brca1+/− tumor cells, while Pdgfrβ expression was found in 2–5% of p18−/− tumor cells and was much weaker in intensity." (PMID 33478572, 2021). "We transfected Pdgfrβ CRISPR/Cas9 KO plasmids (encoding GFP) into p18−/−;Brca1MGKO primary tumor cells." (PMID 33478572, 2021). "During the revascularization phase, tumours obtained following treatment with regorafenib and PDGFRβ antibodies were less revascularized and their CD31 density was remarkably lower than that of tumours obtained following treatment with regorafenib and IgG." (PMID 34035882, 2021). "Several other markers such as vimentin and PDGFRβ can detect both fibroblasts and myofibroblasts in the tumor microenvironment." (PMID 34336660, 2021). "Plerixafor (AMD3100), a CXCR4 antagonist, inhibits the BM-mediated tumor vasculature in ES by reducing PDGFRβ expression through the disruption of the SDF-1α/CXCR4 axis." (PMID 32754598, 2020). "Given the well-documented importance of PDGF-BB and PDGFRβ signaling for pericyte recruitment to the vasculature, we analyzed the effects of impairing PDGFRβ activity on the tumor vasculature." (PMID 31938055, 2020). "High expression of PDGFRβ and high content of CAFs in the tumor stroma are related to an unfavorable prognosis in breast and prostate cancer, colorectal cancer, and pancreatic carcinoma." (PMID 32756477, 2020). "Recent findings prove that PDGFRβ is expressed on the surface of tumor cells belonging to a subgroup of mesenchymal TNBC with invasive and stem-like phenotype and contributes to drive the metastatic potential and vasculogenic mimicry of these tumors." (PMID 32892748, 2020). "PDGFRβ leads to transactivation of EGFR via the formation of a PDGFRβ/EGFR complex, and imatinib treatment inhibits PDGFRβ-mediated cell proliferation and tumor growth in CC cells." (PMID 32708604, 2020). "Here we show that FGF-2 modulates tumor vessels by recruiting NG2+ pricytes onto tumor microvessels through a PDGFRβ-dependent mechanism." (PMID 32709869, 2020). "Since selective targeting of PDGFRβ by 1-NaPP1 strongly affected tumor growth and vasculature leading to a significant decrease in vessel size in both LLC and B16/PDGF-BB tumors, we studied the effect of 1-NaPP1 treatment on tumor vasculature perfusion." (PMID 31938055, 2020). "In conclusion, we demonstrated that the H2A-YG2 carrier targeted gene delivery to PDGFRβ-positive tumor stromal cells." (PMID 32751200, 2020). "The role of THBS4 in cancer has primarily been focused on tumor adhesion, migration, invasion, and angiogenesis while the role of PDGFRβ has been extensively studied in epithelial-mesenchymal transition (EMT) and metastasis." (PMID 32899998, 2020). "Imatinib is used as first line therapy in CML and GIST, based on its ability to target Bcr-Abl, c-Kit and PDGFRβ expressed by the tumor cells." (PMID 31938055, 2020). "Targeting of PDGFRβ kinase activity led to a significant decrease of PDGFRβ+ pericyte coverage of tumor vessels in LLC and B16/PDGF-BB tumors treated with either 1-NaPP1 or imatinib." (PMID 31938055, 2020).
tumor (continued). "Our data support the notion that selective targeting of host PDGFRβ gives a treatment benefit in preclinical tumor models with strong paracrine PDGF-BB stimulation." (PMID 31938055, 2020). "Consistent with their synergistic antitumor activity, combination of VEGF and PDGFRβ blockades markedly inhibited tumor angiogenesis, blood perfusion, leakiness." (PMID 32709869, 2020). "B16 tumors, which comprise low PDGF-BB paracrine signaling, showed a trend towards decreased PDGFRβ+ pericyte coverage of tumor vessels after treatment with 1-NaPP1 as well as imatinib, whereas no change was observed on NG2+ pericyte coverage." (PMID 31938055, 2020). "Although the study of NRP1 in GC remained limited, it was reported that the high expression of NRP1 due to hypomethylation was co-expressed with PDGFRB and was significantly correlated with tumor malignant phenotypes with poor prognosis." (PMID 32903845, 2020). "The role of TGFβ in CRC is also of interest, as it has been shown to be an upstream signal of PDGFRβ in tumor cells, and is involved in angiogenesis through THBS4." (PMID 32899998, 2020). "PDGFRB has been independently gained eight times, often at high copy number; interestingly, this has occurred three times in tumours at a single location, the Freycinet Peninsula." (PMID 33232318, 2020). "To this aim, we used an aptamer and a mAb that we previously validated as high affinity binders and inhibitors of PDGFRβ and PD-L1, respectively, in different tumor types including TNBC." (PMID 32892748, 2020). "The stimulation of PDGFRβ has been shown to increase the coverage of the tumor vessels and subsequently to improve vessel function." (PMID 33568892, 2019). "A large set of studies have demonstrated the importance of PDGFRβ-positive perivascular cells, or pericytes, in tumor vessel stabilization." (PMID 31308421, 2019). "For instance, PDGF receptor β (PDGFRβ) has been reported to play an important role in recruitment of MSCs towards tumor sites." (PMID 31205939, 2019). "Experimental studies in different animal cancer models have shown that reduction of pericyte recruitment, through interference with the PDGFRβ signaling in pericytes, negatively affects tumor angiogenesis and also reduces tumor growth." (PMID 31308421, 2019). "Immunostaining of αSMA and PDGFRβ, common markers of activated fibroblasts and pericytes, was used to quantify the relative amount of activated fibroblasts in the tumor stroma." (PMID 30876468, 2019). "Depletion of CD8+ T cells significantly reduced the anti-tumor efficacy of triple combination treatment suggesting that CD8+ cytotoxic T cells are critical for anti-tumor efficacy of MEK1/2-JAK2/PDGFRβ inhibition in triple combination therapy." (PMID 30777101, 2019). "In the ccRCC tumor tissues, PDGFRβ was present in the vimentin-positive stroma cells surrounding the tumor islands and blood vessels." (PMID 31690270, 2019). "The shift was significantly skewed for PDGFRα expression in tumour cells, which was up-regulated in lymph node metastases and recurrences, and for stromal PDGFRβ expression, which was down-regulated in recurrences." (PMID 29380207, 2018). "Stromal cells showed high expression of PDGFRα in 243 (50%) and PDGFRβ in 128 (27%) of the evaluated primary tumours." (PMID 29380207, 2018). "While this was confirmed in our VM− tumor models, anti‐PDGFRβ treatment also reduced the VM‐characteristic vascular structures in different VM+ tumor models." (PMID 30101525, 2018). "U87 xenograft brain sections were stained for the endothelial marker CD31 to determine tumor vascularization, and for PDGFRβ, SMA, and Col IV to assess blood vessel maturation." (PMID 30065025, 2018). "Similar to myofibroblasts in wounds or fibrotic tissues, tumor-associated fibroblasts are known to overexpress ACTA2, FAP and PDGFRB." (PMID 30473751, 2018).
tumor (continued). "About PDGFRβ expression in tumor and vascular lacunae according to CDCP1 levels, 72.4% (21/29) of PDGFRβ-positive cases in tumor nests were CDCP1-positive (p = 0.0429; Fisher’s exact test)." (PMID 29792166, 2018). "Along with the mentioned proteins, we also found with Western blot analysis the AI tumorspheres to significantly up-regulate other highly tumorigenic proteins involved in aggressive tumor behavior, including PDGFRβ, VEGFR2 and EGFR compared to the AD cells." (PMID 29298329, 2018). "More recently, it was shown that PDGF‐B/PDGFRβ signaling is also involved in the recruitment of mesenchymal stem cells and their subsequent differentiation into pericytes that promote tumor vasculogenesis." (PMID 30101525, 2018). "As the PDGF–PDGFR system is the best-characterized signaling pathway in pericyte recruitment in angiogenic vessels, we investigated the effects of PDGFRα and PDGFRβ specific blockades in pericyte recruitment in FGF2+ tumor models." (PMID 29423271, 2018). "Regarding the role of PDGFRβ, it is crucial for the vasculogenic properties of tumor cells, and therefore, its role in tumorigenesis mainly accounts for the activation of migration/invasion/angiogenesis pathways in cancer cells." (PMID 29792166, 2018). "In both in vitro and in vivo experiments, [125I]4 showed a significantly higher tumor uptake with high PDGFRβ expression than [125I]5." (PMID 29991770, 2018). "[77Br]2 uptake in tumors should be PDGFRβ specific, and [77Br]2 should bind to the ATP-binding site of PDGFRβ in the tumor cell." (PMID 29991770, 2018). "This study indicates that PDGFRβ and TGFβ-TGFβR signaling cooperatively promote the differentiation of MSCs into CAFs in tumor microenvironments independently of canonical PDGF-PDGFR signaling." (PMID 30344924, 2018). "Almost all tumours with high stromal cell PDGFRβ and high tumour cell PDGF-CC also had high PDGFRα, either in stromal or tumour cells." (PMID 29380207, 2018). "This showed a significant association between increasing expression of both PDGFRα and PDGFRβ, and increasing PDGF-CC levels (P < 0.001 for tumour and stromal cell PDGFRα expression, P = 0.004 for stromal cell PDGFRβ expression)." (PMID 29380207, 2018). "Both aptamers functioned as effective tumor delivery agents in, respectively, Axl-expressing and PDGFRβ-expressing U87MG cells." (PMID 30340426, 2018). "NG2 expression was decreased on tumor-derived PDGFRb+PDFGRa+ subset (R1 gate) compared to their matched normal counterpart (1029 ± 1229 versus 1504 ± 1598, respectively, n = 10 biological replicates)." (PMID 28878242, 2017). "Tumor-associated pericytes displayed a rather heterogeneous pattern of expression of the typical pericyte markers, CD146, NG2, and PDGFRβ, compared with normal pericytes." (PMID 28553358, 2017). "We observed that imatinib, as expected, decreased the number of PDGFRβ-positive cells by approximately 50% in all three tumor types." (PMID 28231806, 2017). "We have now shown that the combined effects of the downregulation of PDGFRβ and the changes in pericyte adhesion upon deletion of α6β1-integrin induces destabilisation of tumour blood vessels." (PMID 28289267, 2017). "To exclude the possibility that Tie1‐positive cells originated from tumor‐associated tissues, we further investigated other typical marker proteins (CD31, CD45, and PDGFRβ for endothelial cells, white blood cells and fibroblasts, respectively)." (PMID 28464467, 2017). "Since imatinib inhibits the PDGFRβ kinase these data show that imatinib indeed was active in all three tumor models." (PMID 28231806, 2017). "In our previous work, we prepared the monomeric Z09591 affibody, designated ZPDGFRβ, and found that it showed PDGFRβ-dependent pericyte binding and thus increased the tumor uptake of fused anti-cancer proteins." (PMID 29182023, 2017).